SP1 (Sp1 transcription factor)
Diseases named in the same sentence as SP1 in open-access papers (continued):
Sharing a sentence is not in itself a finding about the gene and the disease.
breast carcinoma (continued). "SP1 controls the proliferation of breast cancer cells by interacting with insulin-like growth factors I receptor (IGFIR)." (PMID 34257529, 2021). "According to UALCAN database, breast cancer, ovarian cancer, colon cancer and lung adenocarcinoma display an elevated SP1 expression in comparison with normal tissues." (PMID 34257529, 2021). "TIMELESS plays a crucial role in the self-renewal process of breast CSCs and interacts with Sp1/c-jun to induce miR-5188 expression by promoting c-jun-mediated transcription, thus promoting breast cancer progression." (PMID 32528520, 2020). "Multiple studies have confirmed the important regulatory role of SP1 in esophageal cancer 19, pancreatic cancer 20 and breast cancer." (PMID 31892989, 2020). "For the mechanism investigation, metformin inactivates oncogenic HMGA2 transcription through reducing transcription factor Sp1, leading to breast cancer growth inhibition." (PMID 32031335, 2020). "Our data showed that the binding of Sp1 to HMGA2 promoter was abrogated by metformin in breast cancer cells." (PMID 32031335, 2020). "It is reported that Sp1 overexpression predicts poor prognosis in some breast cancer patients while Jumonji domain-containing 2A-dependent inhibition Sp1 promotes metastasis in advanced breast cancer." (PMID 33093451, 2020). "Noticeably, lncRNA AGAP2-AS1 was upregulated and transcriptionally induced by SP1 in breast cancer metastasis." (PMID 32929060, 2020). "HBXIP can act as a transactivator by activating certain genes including c-Myc, E2F1, STAT4, and Sp1 to play a crucial role in the progression of breast cancer." (PMID 32850453, 2020). "A previous study showed that TSPO expression is regulated by the binding of Sp1, Sp3 and/or Sp4 to the proximal promoter region in human breast cancer cell lines, and a similar sequence was observed in the mouse Tspo gene." (PMID 31536603, 2019). "RNA-seq analysis of breast cancer patient’s samples from the TCGA database inferred the positive correlation between Sp1 and TMBIM6 gene expressions." (PMID 31336725, 2019). "The TGF‐β‐induced EGFR expression was more strongly inhibited by the double suppression of Smad3 and Sp1 expression than by the single‐Sp1 or single‐Smad3 siRNA‐transfected breast cancer cells." (PMID 29215776, 2018). "The transcription factor SP1 has been considered as an oncoprotein which is highly expressed in early-stage breast cancer." (PMID 29651880, 2018). "In this study, the Sp1 expression in breast cancer cells is increased after TGF‐β treatment is administered." (PMID 29215776, 2018). "Taken together, KDM4A seems to play an important role in SP1 downregulation in advanced breast cancer cells." (PMID 29651880, 2018). "TINCR was aberrantly up-regulated by SP1, which in turn stimulated cell proliferation, anchorage-independent growth and suppressed cell apoptosis in breast cancer." (PMID 29614984, 2018). "In keeping with previous studies that mithramycin A, a Sp1 inhibitor, markedly reduced basal survivin levels in colorectal cancer and breast cancer cells, we noted that mithramycin A also caused survivin reduction in FaDu cells (unpublished data)." (PMID 29545751, 2018). "Compared to SP3, SP1 has been extensively studied in breast cancer, thyroid cancer, hepatocellular cancer, pancreatic cancer, colorectal cancer, gastric cancer and lung cancer." (PMID 30386180, 2018). "To further confirm the role of Sp1 and Smad3 in TGF‐β‐induced enhancement of the migration and invasion abilities of breast cancer cells, we knocked down the expression of Sp1 or Smad3 using two different siRNA sequences in two breast cancer cells." (PMID 29215776, 2018). "But in advanced breast cancer cells, SP1 is downregulated due to its inhibitory roles for migratory and invasive abilities." (PMID 29651880, 2018). "The major finding of the present study is that miR-506 inhibits migration and invasion of breast cancer cell lines through an undescribed pathway SP1/SP3/DNMT1/MEG3." (PMID 30386180, 2018).
breast carcinoma (continued). "I3C-induced inhibition on MMP-2 by blocking the ERK/Sp1-mediated gene transcription also contributed to its anti-invasive action on breast cancer cells." (PMID 28698459, 2017). "For TINCR, this lncRNA is induced by SP1 and promotes cell proliferation in gastric cancer and oesophageal squamous cell carcinoma, a finding that is in accordance with our results in breast cancer." (PMID 28738804, 2017). "According to GO analyses, the seed of cluster 1 (SP1) plays some roles in breast cancer, choline metabolism and GnRH signaling pathway." (PMID 29379595, 2017). "They studied 336 pairs of breast cancer cases and used SP1 and IE2 antibodies, and CB11 (Ventana, USA) for ER, PR, and Her-2, respectively." (PMID 29531544, 2017). "Using breast cancer tissue from 202 patients diagnosed with breast cancer since 2003 to 2004, we tested the level of SP1 mRNA expression and analyzed the effect of SP1 expression level on DRFS." (PMID 27545642, 2016). "Reporter assays have shown that AP-1 and Sp-1 sites at the promoter downstream are required for ERα−mediated PGR activation in MCF7 breast cancer cells." (PMID 27007157, 2016). "A recent study reported that SP1 is a direct target of miR-200b and is involved in miR-200b-induced suppression of breast cancer cell growth." (PMID 26882471, 2016). "Altogether, these data demonstrate that from the set of antibodies commonly used for breast cancer diagnosis, the SP1 antibody is the only one able to recognize the ERα46a isoform by immunohistochemistry." (PMID 27927249, 2016). "In MCF7 breast cancer cells Sp1 is involved in the basal and estrogen-induced gene expression and cell cycle progression and in gastric tumor cells knock down of Sp1 expression suppressed angiogenesis." (PMID 25923237, 2015). "More recently, anti-ERα rabid monoclonal antibody SP1—which recognizes C-terminal of ERα—has been introduced and is reported to have higher sensitivity and an 8-fold higher affinity in breast carcinomas for the detection of ERα, compared with ID5." (PMID 26318038, 2015). "Our observations consisted with previous findings that Sp1 was being involved in the basal transcriptional activation of HIF-1α in breast cancer cells." (PMID 26640316, 2015). "In our study, we further detected the established collaboration of E2F family members with Sp1, c-Myc and NF- κB1, each of which plays a critical role in breast cancer." (PMID 26627005, 2015). "Sp1 is overexpressed in gastric cancer, in breast cancer, in thyroid tumors and in pancreatic adenocarcinoma, Sp1 overexpression is associated with higher grade and lymph node metastasis." (PMID 25923237, 2015). "Hypoxic induction of the tenascin-X (TNXB) gene in the breast cancer cell line MCF-7 involves another type of Sp1 activation mechanism." (PMID 26703734, 2015). "Another study in breast cancer epithelial cells found that EGFR is repressed by binding of the TIEG1/HDAC1 complex to SP1 sites on the EGFR promoter resulting in suppression of histone acetylation." (PMID 26243279, 2015). "Studies have also revealed that Sp1 plays a role in cell cycle arrest during the G0/G1 phase in human prostate cancer cells and human breast cancer cells." (PMID 24434641, 2014). "This pathway was also reported in another study in breast cancer cells where the authors showed that FGF-2 down-regulates TSP50 expression via the ERK/Sp1 pathway." (PMID 25280005, 2014). "Sp1 binds to several G/C-rich elements located within the proximal promoter and initiates the transcription of ER in breast cancer cells together with several co-factors of the basal transcription machinery." (PMID 25149534, 2014). "Sp1, a member of the Sp/Krüppel-like transcription factor family, is ubiquitously expressed in normal tissues, but highly overexpressed in ER+ breast cancers." (PMID 25149534, 2014). "One of the most important regulators of ER transcription is Sp1 (specificity protein 1) that is overexpressed in human ER positive (ER+) breast cancers." (PMID 25149534, 2014).
breast carcinoma (continued). "The second region included promoter B with a classical G/C box, which has been previously shown to bind Sp1 in breast cancer cells." (PMID 25149534, 2014). "SP1 overexpression was found in breast cancer, hepatocellular carcinoma, thyroid tumors, and in gastric cancer." (PMID 23437057, 2013). "This is known as transcription factor decoy and Sp1 has already been targeted using this approach in breast cancer." (PMID 23825960, 2013). "miR-22 is a tumor suppressor that induces cellular senescence (by targeting CDK6, SIRT1 and Sp1) and is frequently downregulated in ER+ breast cancer." (PMID 24146960, 2013). "Among the top 20 TF binding motifs enriched at genome-wide PR targets, we found that AP2 and SP1 sites were the most frequent motifs in breast cancer cells, whereas AP1 was the most frequent motif in leiomyoma cells." (PMID 22272226, 2012). "A recent study demonstrated that both single nucleotide polymorphism (SNP) 285 and SNP 309 in MDM2 (murine double mutant 2) are found in breast cancer and can affect the binding of Sp1 to the MDM2 promoter." (PMID 23148884, 2012). "In summary, we found that Sp1/Brg-1 complex is involved in the constitutive expression of the SPARC gene in mammary tumor cells." (PMID 20687958, 2010). "Since Sp1 is ubiquitously expressed, these sites, while necessary, are not sufficient to explain the patterns of gene expression of MsrB1 in various human breast cancer cells." (PMID 17519015, 2007). "We investigated endogenous levels of Sp1, Sp3 and topoisomerase IIα as well as binding of both Sp1 and Sp3 to the GC boxes of the topoisomerase IIα promoter in breast cancer cell lines in vivo after short term doxorubicin exposure." (PMID 17511886, 2007). "The in vivo interactions of Sp1 and Sp3 with the GC elements of the topoisomerase IIα promoter were studied in doxorubicin-treated breast cancer cell lines using chromatin immunoprecipitation assays." (PMID 17511886, 2007). "These include six sister subpopulations derived from a single BALB/cfC3H mouse mammary tumour (lines: 67, 66c14, 168FARN, 4TO7, 68H, 64pT) as well as SP1 spontaneous CBA/J mouse mammary carcinoma." (PMID 1586590, 1992). "Notably, SP1 plays a crucial role in promoting proliferation in breast cancer cells by regulating the expression of insulin-like growth factor-I receptor (IGF1R)." (PMID 40884402, 2025). "Genes that are induced by PR/Sp1 have primarily been observed in T47D breast cancer cells that overexpress PR and include p21/p27, EGFR, PRL receptor and MKP1 that are activated by PR/Sp1; HSPB8 is induced via PRE-(N)X-GC sequence and also includes cyclin D1 as part of the complex." (PMID 39858066, 2025). "Elevated Sp1 levels have been reported in multiple cancers, including gastric cancer (GC), ovarian cancer, pancreatic cancer, hepatocellular carcinoma, glioblastoma, lung cancer, breast cancer, and colorectal cancer (CRC)." (PMID 40869407, 2025). "Sp1, the first identified transcription factor in the specific protein/Kruppel-like factor family, has been reported to promote Cldn1 expression in the intestinal epithelium and human breast cancer epithelium." (PMID 40940777, 2025). "High levels of SP1 protein have been shown to correlate with tumour cell migration and metastasis in a number of tumour models and patient samples, including gastric and breast cancers and WNT signalling activity." (PMID 39748426, 2025).
breast carcinoma (continued). "Additionally, SP1 upregulation is consistently observed across various breast cancer subtypes, including hormone receptor-positive, HER2-positive, and triple-negative breast cancer." (PMID 40884402, 2025). "Zhang et al23 found that the expression of lncRNA AFAP1-AS1 in TNBC tissue is significantly higher than that in normal tissue and other breast cancer subtypes, and that Sp1 is upregulated through sponging by miR-2110, thereby promoting the proliferation, migration and invasion of TNBC cells." (PMID 39991583, 2025). "Consequently, targeting SP1 has emerged as a potential therapeutic strategy for breast cancer treatment." (PMID 40884402, 2025). "PSAT1 could increase distant breast cancer metastasis through upregulation of the p-AKT/SP1/ITGA2 axis." (PMID 39199378, 2024). "Mechanistically, PSAT1 facilitated breast cancer metastasis via the p-AKT/SP1/ITGA2 axis." (PMID 39199378, 2024). "SP1 suppression may be a potential intervention strategy for inhibiting the migration of breast cancer cells and slowing down the progression of TNBC." (PMID 37686205, 2023). "Both Sp1 and Sp3 were associated with HDAC activity in human breast cancer cells." (PMID 37764768, 2023). "In breast cancer cells under hypoxic conditions, SP1 acts as a transcriptional activator." (PMID 36077352, 2022). "Finally, licochalcone A displays proapoptotic and antiproliferative effects in breast cancer cells via modulation of transcription factor Sp1 (Sp1) and apoptosis-related proteins." (PMID 35082907, 2022). "Our findings demonstrated that AFAP1-AS1 could modulate the progression of breast cancer cells and affect tumorigenesis in mice by acting as a miR-2110 sponge, resulting in regulation of Sp1 expression." (PMID 34145213, 2021). "Taken together, ursolic acid, the bioactive compound of Oldenlandia diffusa, could dramatically suppress breast cancer growth and metastasis by impairing glycolytic metabolism via activating SP1/Cav-1 signaling." (PMID 34568078, 2021). "In this study, we systematically demonstrated that ursolic acid, the bioactive compound of Oldenlandia diffusa, could dramatically suppress breast cancer growth and metastasis by impairing glycolytic metabolism via activating SP1/Cav-1 pathway." (PMID 34568078, 2021). "More importantly, CHIP-PCR assay validated that ursolic acid could promote the binding of SP1 with CAV1 promoter region of breast cancer cells, while SP1 knockdown could partially abrogate that." (PMID 34568078, 2021). "SP1-induced upregulation of MyD88 contributes to the chemoresistance of breast cancer." (PMID 34307888, 2021). "In summary, we concluded that metformin could control HMGA2 transcription through targeting Sp1 in breast cancer." (PMID 32031335, 2020). "For example, the TF SP1 activates transcription of the lncRNA AGAP2-AS1 in breast cancer." (PMID 33230459, 2020). "Metformin resists the growth of breast cancer through targeting Sp1/HMGA2 signal." (PMID 32031335, 2020). "Selecting two types of BC cells could help us understanding whether miR-212-3p/Sp1/VEGFA signal axis could regulate different breast cancer subtypes." (PMID 33187481, 2020). "In breast cancer, epigenetic regulators like DNMTs (1/3), HDAC, JARID1B (histone H3 lysine 4 demethylase) and sp1 (Sp1 Transcription Factor) cause both higher and lower expression of several miRNAs including miR-124.3, miR148a, miR-375, miR-152, members of miR-200, let-7 and miR-34 families." (PMID 33050637, 2020). "Studies have shown that HIF-1α could promoted the expression of VEGF-A 51, and it has been reported that SP1 could promote the expression of VEGF-C in breast cancer." (PMID 31892989, 2020). "Further studies will be required to address whether SP1 regulates other lncRNAs in addition to AGAP2-AS1 during breast cancer metastasis." (PMID 32929060, 2020).
breast carcinoma (continued). "However, the observed trends towards an increased breast cancer risk and a poor survival are at odds with the proposed molecular function of the SNP285C-allele to reduce binding of SP1 and expression of MDM2." (PMID 30691044, 2019). "We then assessed the functional relevance of combined STAT3 and SP1 activity in breast cancer." (PMID 30654518, 2019). "RhoU down-regulation by silencing or treatment with JNK, SP1 or STAT3 inhibitors leads to impaired migration and invasion in basal-like MDA-MB-231 and BT-549 cells, suggesting that STAT3 and SP1 can cooperate to induce high RhoU expression and enhance breast cancer cells migration." (PMID 30654518, 2019). "Moreover, ST6Gal-I is upregulated via SP-1-dependent transcription during TGFβ-induced epithelial to mesenchymal transition in breast cancer cells." (PMID 31610800, 2019). "Furthermore, RNA-seq data analysis from TCGA data showed a positive correlation between TMBIM6 and Sp1 expression in breast cancer patient’s sample." (PMID 31336725, 2019). "To investigate whether Sp1 and Smad3 elicit a synergetic effect on TGF‐β‐induced upregulation of EGFR expression, on the basis of Smad3 knockdown, we used the Sp1 inhibitor MTM to treat breast cancer cells." (PMID 29215776, 2018). "Consequently, TGF‐β failed to upregulate the mRNA and protein expression of EGFR in Sp1‐silenced breast cancer cells." (PMID 29215776, 2018). "Taken together, our data demonstrated SP1 stimulated TINCR overexpression in breast cancer." (PMID 29614984, 2018). "As SP1 is involved in TGFβ1‐induced MET expression in renal epithelial cells, MET might be also regulated by miR‐128‐3p via SP1 in breast cancer." (PMID 30004628, 2018). "Moreover, quantitative analysis suggested that Sp1 and Smad3 caused an additive effect on EGFR expression in breast cancer cells." (PMID 29215776, 2018). "Similarly, VEGF regulation by estrogen in endometrial and breast cancer cells involves interactions of ER-α and Sp1 (or Sp3) with GC boxes in the core promoter region of VEGF." (PMID 28394264, 2017). "Accumulating data has revealed that SP1 is overexpressed in breast cancer and gastric cancer." (PMID 28209170, 2017). "Direct transcriptional repression of Sp1 by JMJD2A also promotes metastasis of breast cancer." (PMID 28212444, 2017). "Moreover, I3C downregulated expression of telomerase gene through disruption of the combined ERα- and Sp1-driven transcription of hTERT gene expression, leading to a cell cycle arrest in breast cancer cell." (PMID 28698459, 2017). "Lastly, we validated the impact of SP1 expression on breast cancer disease progression." (PMID 27545642, 2016). "In breast cancer, miR-22 could indirectly inhibit CD147-associated tumor invasion and metastasis by repressing Sp1 expression, and form an auto-regulatory loop with Sp1 by binding to the miR-22 promoter to inhibit miR-22 transcription." (PMID 27829234, 2016). "Furthermore, Cheng and Hung found that SAHA, a potent HDACi, inhibits VEGF-C expression in breast cancer cells via Sp1-dependent transcriptional repression." (PMID 27716272, 2016). "SP1 is known to be involved in cell proliferation, apoptosis, and cell differentiation and transformation, and has been reported as a prognostic marker for breast cancer." (PMID 25961905, 2015). "Furthermore, in breast carcinomas, SP1 was recognized as a more reliable prognostic factor and a superior predictor of response to endocrine therapy compared with ID5." (PMID 26318038, 2015).